HOXA5 (homeobox A5)
Diseases named in the same sentence as HOXA5 in open-access papers (continued):
Sharing a sentence is not in itself a finding about the gene and the disease.
metabolic disease (4 papers, 2017 to 2025). A congenital disorder (due to inherited enzyme abnormality) or acquired (due to failure of a metabolically important organ) disorder resulting from an abnormal metabolic process. "Thus, HOXA5 stands out as an essential regulator of adipogenesis—both in vitro and in vivo—making it, along with its gene network, an intriguing molecular target for the treatment of AT dysfunction and associated metabolic diseases." (PMID 37626900, 2023). "Epigenetics adds a further layer of complexity to HOXA5 gene regulation in relation to metabolic diseases." (PMID 37626900, 2023). "Although further research is needed, mainly regarding the adverse effects of these agents on off-target genes, epigenetic modifications specifically targeting HOXA5 appear to be a promising strategy for precision medicine in metabolic diseases." (PMID 37626900, 2023). "In this review, we highlighted the relevant role of the transcription factor HOXA5 in the pathogenesis of metabolic diseases." (PMID 37626900, 2023). "As DNA methylation is the primary mechanism by which HOXA5 become dysregulated, research on drugs targeting methylation at the HOXA5 locus appears promising for treating metabolic diseases." (PMID 37626900, 2023). "Methylation events complicate the regulation of the HOXA5 gene in relation to metabolic diseases." (PMID 40564006, 2025). "Moreover, considering the susceptibility of epigenetic changes to reversal through targeted interventions, we discuss the potential therapeutic value of targeting HOXA5 DNA methylation changes in the treatment of metabolic diseases." (PMID 37626900, 2023). "The effects of histone modifications and ncRNA on the development of metabolic diseases have been extensively discussed elsewhere and will not be covered in this review, which is focused on the role of DNA methylation in regulating the HOXA5 gene in the context of metabolic disorders." (PMID 37626900, 2023). "Additionally, creating an animal model with a targeted deletion of HOXA5 specifically in AT holds promise as an exciting approach to further investigate its role in metabolic disease development." (PMID 37626900, 2023). "Epigenetics adds complexity to HOXA5 gene regulation in metabolic diseases." (PMID 37626900, 2023).
adenocarcinoma (3 papers, 2009 to 2019). A common cancer characterized by the presence of malignant glandular cells. "Another finding of our study was the remarkable regulation of hox genes in adenocarcinoma, for example Hoxa5, Hoxb5, Meis1 and Meis2." (PMID 19812696, 2009). "Furthermore some of the homeobox genes, e.g. Hoxa5, Hoxb5, Meis1 and Mrg1 were up to 9-fold repressed in adenocarcinomas." (PMID 19812696, 2009).
infection (3 papers, 2017 to 2022). The state of being infected such as from the introduction of a foreign agent such as serum, vaccine, antigenic substance or organism. "A Hoxa5:a7 ESC clone expressing Cas9 was transduced with the pooled lentiviral sgRNAs at a low multiplicity of infection (~0.4), as applied previously, such that each transduced cell expressed a single sgRNA." (PMID 35145304, 2022). "At timepoints after day 6, infection and selection with empty vector skewed the expression of genes such as Hoxa5, suggesting that infection and selection were skewing the populations of cells in the culture." (PMID 28537559, 2017).
hematologic malignancies (2 papers, 2020 to 2025). "HOXA5 plays a dual role in solid versus hematologic malignancies and serves as a key spatial immune regulator." (PMID 41209012, 2025).
HOXA5 also shares sentences with these, for which no sentence is quoted: melanoma (3 papers); oral squamous cell carcinoma (3); pancreatic cancer (3); inflammatory bowel disease (2); nasopharyngeal carcinoma (2); serous ovarian carcinoma (2); acute lung injury (1); Allergy (1); Alzheimer disease (1); anencephaly (1); blood tumors (1); cardiac hypertrophy (1); childhood asthma (1); Chronic Myeloid Leukemia (1); colorectal adenocarcinoma (1); cutaneous melanoma (1); depressive disorder (1); embryonic carcinoma (1); endocrine disorders (1); esophageal cancer (1); gastrointestinal stromal tumor (1); genetic disorders (1); Gliosis (1); head and neck squamous cell carcinoma (1); hyperglycaemia (1); hyperplasia (1); Hypertension (1); inflammation (1); insulinoma (1); invasive breast carcinoma (1).
A further 20 diseases each share a sentence with HOXA5 in 1 paper.